MALAT1 (metastasis associated lung adenocarcinoma transcript 1)
Diseases named in the same sentence as MALAT1 in open-access papers (continued):
Sharing a sentence is not in itself a finding about the gene and the disease.
lung cancer (continued). "High RNA level of MALAT1 contributed to a poor outcome of lung cancer patients, and Kaplan–Meier analysis showed that high RNA level of MALAT1 was related to poor overall survival in lung cancer patients." (PMID 34308750, 2021). "Gutschner and colleagues conducted loss-of-function studies in which an antisense oligonucleotide inhibitor of MALAT1 was introduced to lung cancer xenograft mice models." (PMID 33803619, 2021). "High mRNA level of MALAT1 was related to better OS or FP of lung cancer patients in sex, stage, and chemotherapy." (PMID 34308750, 2021). "Metastasis-associated lung adenocarcinoma transcript 1 (MALAT1) is a highly conserved and abundant lncRNA, which was originally described to play crucial roles in lung cancer metastasis." (PMID 33777808, 2021). "MALAT1 expression has been shown to be either upregulated (lung cancer, hepatocellular carcinoma) or downregulated (colorectal cancer, breast cancer), indicating that its role is either cancer-promoting or tumor-suppressing." (PMID 33477898, 2021). "These suggested that MALAT1 expression has also influenced lung cancer patient prognosis in early stage." (PMID 34308750, 2021). "In this study, we showed that MALAT1 knockdown blocked the proliferation, colony formation, migration and invasion ability of lung cancer cells through the downregulation of expression levels of UBE2C in a substantial number lung cancer cell." (PMID 34257576, 2021). "By qRT-PCR analysis for 124 lung cancer patients, the rate for MALAT1 RNA level with upregulaton was 88.7%, thus indicating the oncogenic roles of MALAT1 in lung cancer patients." (PMID 34308750, 2021). "By analyzing the differential gene expression of cells before and after interference, it was found that MALAT-1 controlled the migration capability of lung carcinoma cells by regulating the expression of motion-related genes." (PMID 34858541, 2021). "In this study, we detected MALAT1 expression level in lung carcinoma cell lines and the role of MALAT1 in cell proliferation, colony formation, migration and invasion were examined." (PMID 34257576, 2021). "Collectively, these findings suggest that MALAT1 stimulates lung carcinoma progression via the miR-491-5p/UBE2C axis." (PMID 34257576, 2021). "In order to explore the mechanism of MALAT-1 promoting lung carcinoma cell migration, a study used siRNA to interfere with MALAT-1 expression and found that cell motility decreased significantly." (PMID 34858541, 2021). "Collectively, MALAT1 downregulation suppressed lung carcinoma progression by regulating the miR-491-5p/UBE2C axis." (PMID 34257576, 2021). "Taken together, we demonstrated that the lncRNA MALAT1 is involved in lung carcinoma development by regulating the expression of miR-491-5p and UBE2C." (PMID 34257576, 2021). "Previously, a large amount of evidence has shown that MALAT1 plays an important role in the tumorigenesis of many types of tumors, including lung carcinoma, breast cancer and pancreatic cancer." (PMID 34257576, 2021). "Metastasis-associated lung adenocarcinoma transcript 1 (MALAT1), also called non-coding nuclear-enriched abundant transcript 2 (NEAT2), was originally identified as being associated with lung cancer metastasis." (PMID 32138732, 2020). "Subcutaneous injection of ASOs targeting the lncRNA MALAT1 is sufficient to reduce the formation of breast and lung cancer metastasis in MMTV-PyMT mouse mammary carcinoma and lung cancer xenograft models, respectively." (PMID 33352769, 2020). "In vivo injection of MALAT1 ASOs also successfully decreased the expression of MALAT1 and suppressed lung cancer progression, which suggests that targeting MALAT1 in lung cancer patients is a potential and promising clinical therapy." (PMID 33343366, 2020).
lung cancer (continued). "Metastasis-associated lung adenocarcinoma transcript 1 (MALAT1), also known as nuclear-enriched transcript 2, has been identified as a prognostic biomarker of lung cancer metastasis and has been linked with several other types of human tumors." (PMID 32384281, 2020). "MALAT1 can be used to predict survival chance ofstage I lung cancer or squamous cell cancer patients andit is phase and histologically specific to the metastasis ofNSCLC patients." (PMID 31863664, 2020). "Metastasis-associated lung adenocarcinoma transcript 1 (MALAT1) is a biomarker for lung cancer metastasis and can govern hallmarks of lung cancer metastasis." (PMID 33333725, 2020). "First, all papers included in this study used lung cancer tissue for detection of MALAT-1 expression." (PMID 33052949, 2020). "The detection of MALAT-1 in blood specimens needs to be further verified by large and high-quality literature for predicting the prognostic value of lung cancer." (PMID 33052949, 2020). "Theoretically, the expression of MALAT-1 detected in plasma or serum should be included to predict the prognosis of lung cancer." (PMID 33052949, 2020). "MALAT-1 was also able to prevent lung cancer cell apoptosis, alternatively leading to proliferation, cell migration and invasion." (PMID 32641036, 2020). "MALAT1 presents differences in the degree of methylation in lung cancer tissues and normal tissues, demonstrating that its function as proto-oncogene can be regulated by methylation." (PMID 33371204, 2020). "Metastasis-associated lung adenocarcinoma transcript-1 (MALAT1, also known as NEAT2) was initially discovered in lung cancer and has been subsequently detected to be overexpressed in multiple tumors as a negative prognosis factor." (PMID 32257946, 2020). "Pre-clinical studies using breast and lung cancer models targeting Malat1 using antisense Gapmer oligonucleotides have resulted in an anti-tumor and anti-metastatic outcome in both studies." (PMID 32503170, 2020). "MALAT1 (Metastasis-associated lung adenocarcinoma transcript 1) and HOTAIR (HOX transcript anti-sense RNA) are well known lung cancer associated lncRNAs, with various functions in biological courses." (PMID 31901898, 2020). "MALAT1 was one of the first human lncRNAs to be discovered in samples of metastatic lung cancer cells." (PMID 31745703, 2020). "For instance, miR-101 and miR-217 regulate the half-life of metastasis associated lung adenocarcinoma transcript 1 (MALAT1) in carcinoma cells, while miR-449a silences the nuclear enriched abundant transcript 1 (NEAT1) in lung cancer." (PMID 31732741, 2020). "Studies have confirmed that MALAT1 is a valuable prognostic marker and a promising therapeutic target in lung cancer metastasis." (PMID 32993558, 2020). "The lncRNA metastasis-associated lung adenocarcinoma transcript 1 (MALAT1), also known as nuclear-enriched transcript 2 (NEAT2), is involved in osteoporosis, as well as serving as a prognostic biomarker for lung cancer metastases." (PMID 32664424, 2020). "Growing evidence has indicated that the lncRNA MALAT1 contributes to tumor development in several types of human cancers, such as lung cancer and colorectal cancer." (PMID 32209115, 2020). "Due to the high diagnostic sensitivity of serum MALAT1 as a reference for NSCLC, the misdiagnosis rate of lung cancer is low, which indicates that serum MALAT1 has better clinical application value in lung cancer screening." (PMID 31846184, 2020). "We made use of zinc-finger nucleases that were previously used to knock out MALAT1 in A549 lung cancer cells to deplete MALAT1 in A375m2 and A2058 cells." (PMID 32369931, 2020). "Former studies have illustrated that MALAT1 upregulation promoted tumorigenesis in numerous cancers, including in esophageal carcinoma, prostate cancer, hepatocellular carcinoma, and lung cancer." (PMID 30771618, 2019).
lung cancer (continued). "The lncRNA metastasis-associated lung adenocarcinoma transcript 1 (MALAT1), widely expressed in mammal tissue, was first identified in lung cancer." (PMID 31850199, 2019). "Metastasis-associated lung adenocarcinoma transcript 1 (MALAT1), also known as nuclear-enriched transcript 2 (NEAT2), has been identified as a prognostic biomarker for lung cancer metastasis and has been linked with several other types of human tumors." (PMID 31659145, 2019). "The expression level of lncRNA MALAT1 was upregulated in acute myeloid leukemia, and MALAT1 knockdown in lung cancer cells led to upregulation of miR-101-3p expression, and then miR-101-3p reduced myeloid cell leukemia 1 (MCL1) expression by binding to 3’-UTR." (PMID 30925672, 2019). "Metastasis-associated in lung adenocarcinoma transcript 1 (MALAT1), an lncRNA that was first recognized as a prognostic parameter for patient survival of stage I lung cancer, is up-regulated in multiple human malignancies, including BC." (PMID 31387972, 2019). "The antimetastatic effect of MALAT1 targeting by ASO was also reported in a lung cancer xenograft model, highlighting the potential of MALAT1 as a therapeutic target in multiple tumors." (PMID 31174564, 2019). "Many studies had shown that lncRNAs are associated with lung cancer, such as H19, ATB, CDKN2B-AS1, and MALAT1." (PMID 31775885, 2019). "For example, MALAT1 was found to be overexpressed in many solid tumors such as hepatocellular carcinoma and lung cancer." (PMID 30732558, 2019). "In a study, MALAT1 expression also significantly increased in lung cancer cells as compared to NC and adjacent lung cancer tissue." (PMID 32099603, 2019). "Another study demonstrated that the lncRNA MALAT1 contributes to cisplatin resistance and modulates P-gp expression in lung cancer via the STAT3 pathway." (PMID 31920517, 2019). "It was reported recently that SOX9 participates in the feedback loop of MALAT1 (metastasis associated lung adenocarcinoma transcript 1)-miR-101-SOX9, which modulates the chemoresistance of lung cancer cells to Cisplatin via the Wnt signaling pathway." (PMID 31060551, 2019). "On one hand, upregulation of MALAT1 was reported in lung cancer, hepatocellular carcinoma, breast cancer, and colorectal carcinoma, which has been extensively reviewed previously." (PMID 30781877, 2019). "The MALAT1/miR-145-5p/NEDD9 axis was described in lung cancer: MALAT1 sponges miR-245-5p to amplify NEDD9 expression." (PMID 31404273, 2019). "Collectively, both in vitro and in vivo experiments demonstrated that MALAT1 knockdown promotes cisplatin-induced apoptosis in lung cancer cells." (PMID 29484127, 2018). "In lung cancer, only a small part of lncRNAs, such as H19, HOTAIR, MALAT1, ANRIL, and GAS5 have been identified to be tumor-associated especially in lung cancers." (PMID 30154938, 2018). "The MALAT1 lncRNA is highly conserved among mammals and was initially discovered with established roles in lung cancer." (PMID 30150986, 2018). "For example, MALAT1, a critical regulator of the metastasis phenotype in lung cancer cells, potentially regulated the expression of UBN2 and NEAT1 (row two)." (PMID 29303984, 2018). "The overall expression of MALAT1 was higher in cisplatin-resistant lung cancer tissues than in cisplatin-sensitive samples." (PMID 29484127, 2018). "MALAT1 knockdown in lung cancer cells resulted in miR-101-3p upregulation and increased cisplatin sensitivity." (PMID 29484127, 2018). "We showed that high MALAT1 expression in lung cancer tissues is inversely correlated with overall survival." (PMID 29484127, 2018). "Lung cancer patients with high MALAT1 expression demonstrated poor prognosis and low overall survival." (PMID 29484127, 2018). "Then, we cloned MCL1 cDNA sequence lacking the 3’-UTR into pcDNA3.1 plasmid (pcDNA3.1-MCL1) and transfected into lung cancer cells to express MCL1 that was insensitive to MALAT1 or miR-101-3p expression." (PMID 29484127, 2018).
lung cancer (continued). "Since its discovery in 2007, growing evidence has shown that MALAT1 plays a crucial role in the initiation of various cancers, such as lung cancer, bladder cancer, and prostate cancer." (PMID 29631611, 2018). "Malat1 (Metastasis-associated lung adenocarcinoma transcript 1), also called NEAT2, is a lncRNAs discovered in the context of lung cancer and observed to exert a pro-metastatic effect." (PMID 29912916, 2018). "We demonstrated that MALAT1 knockdown leads to miR-101-3p upregulation, which sensitizes lung cancer cells to cisplatin by downregulating MCL1 expression." (PMID 29484127, 2018). "It appeared that Malat1 was predominantly localized in the nucleus, which is consistent with most other published studies in HeLa cells, lung cancer cells, and THP-1 cells." (PMID 29891768, 2018). "CCK8 and flow cytometry analysis showed that miR-101-3p upregulation and MALAT1 knockdown increased cisplatin-induced apoptosis in lung cancer cells." (PMID 29484127, 2018). "MALAT1 knockdown increased cisplatin cytotoxicity of lung cancer cells by promoting apoptosis and reduced tumor growth in xenograft mouse models." (PMID 29484127, 2018). "MALAT1 levels were higher in lung cancer cell lines (A549, H460, H1299, SPC-A1 and A549/DDP) than in normal human bronchial epithelium (NHBE) cell line." (PMID 29484127, 2018). "In this study, we demonstrated high MALAT1 and low miR-101-3p levels in lung cancer A549 and H1299 cells." (PMID 29484127, 2018). "Taken together, these data suggest that miR-101-3p/MALAT1/MCL1 axis is a potential therapeutic target to increase sensitivity of cisplatin-resistant lung cancer cells." (PMID 29484127, 2018). "In lung cancers, several studies showed that MALAT1 regulates proliferation, metastasis and invasion of cancer cells." (PMID 29484127, 2018). "Lung cancer cells tranfected with miR-101-3p mimics or si-MALAT1 showed increased apoptosis upon cisplatin treatment than the corresponding controls." (PMID 29484127, 2018). "We analyzed MALAT1 levels in cisplatin-sensitive and -resistant lung cancer tissue samples (n = 28) by qRT-PCR." (PMID 29484127, 2018). "Recent reports had showed that many of the lncRNAs, including H19, HOTAIR, MALAT1, ANRIL, GAS5, and GAS5-AS1, were tumor-associated, especially in lung cancers." (PMID 30154938, 2018). "To date, SNPs in MALAT1 have been investigated in colorectal cancer, lung cancer, HBV-related hepatocellular carcinoma, as well as pulmonary arterial hypertension." (PMID 29631611, 2018). "Experimental strategies targeting MALAT1 with second generation of naked ASOs demonstrated drastic reduction of lung cancer metastasis in a pulmonary metastatic model in vivo, making MALAT1 a suitable target for anti-metastatic therapy." (PMID 29739426, 2018). "The expression of MALAT1 were at a significantly higher level in four human lung cancer cell lines, A549, H1299, HCC827 and H358, compared to normal cell, BEAS-2B." (PMID 29212230, 2017). "lncRNA MALAT1 has been identified, by Kaplan-Meier analysis, as an effective prognostic parameter for patient survival in stage I nonsmall cell lung cancer." (PMID 28634418, 2017). "One study has shown downregulation of MALAT1 in blood samples of lung cancer patients which was contrary to MALAT1 levels in lung cancer tissues, where it was significantly upregulated." (PMID 28634418, 2017). "Metastasis-associated lung adenocarcinoma transcript 1 (MALAT1) has important roles in regulating the proliferation, invasion and migration of lung cancer cell." (PMID 29212230, 2017). "NEAT1 and MALAT1 function as Oct4 downstream mediators to promote lung cancer proliferation, migration and invasion." (PMID 28615056, 2017). "A total of 654 patients with primary lung cancer (359 lung adenocarcinoma and 295 lung squamous cell carcinoma) and available MALAT1 expression data from white population were included." (PMID 28253859, 2017).
lung cancer (continued). "MALAT1 also served as a marker to predict cancer progression, including multiple myeloma, lung cancer, and cervical cancer." (PMID 28938549, 2017). "Compared to the corresponding normal tissues, MALAT1 showed to be significantly up-regulated (more than 2-fold [i.e., log2 (fold change) > 1]) in 12 lung cancer cases (> 28.57%)." (PMID 29212230, 2017). "Clinically, Oct4/NEAT1/MALAT1 co-overexpression was an independent factor for prediction of poor outcome in 124 lung cancer patients." (PMID 28615056, 2017). "MALAT1 is located at chromosome 11q13.1 and was discovered as a metastatic prognostic marker for lung cancer." (PMID 28938647, 2017). "MALAT1 was found to be upregulated in a variety of human cancers, such as lung cancer, breast cancer, prostate cancer, colon cancer, and liver cancer." (PMID 28389671, 2017). "Clinical studies further validated the importance of Oct4/NEAT1/MALAT1 signaling axis in lung cancer progression." (PMID 28615056, 2017). "Abnormal expression of MALAT1 has also been detected in various types of cancers, including lung cancer, endometrial stromal sarcoma, hepatocellular carcinoma, breast cancer and pancreatic cancer." (PMID 29237426, 2017). "Results showed that MALAT1 knockdown significantly amplified DDP-induced repression of lung cancer cells viability, and reduced the lC50 values from 20.34 (A549/DDP) and 20.83 (H1299/DDP) to 14.19 (A549/DDP) and 13.21 (H1299/DDP)." (PMID 29212230, 2017). "In 42 paired lung cancer tissues and the corresponding adjacent tissues, the expression of MALAT1 was significantly increased in lung cancer tissues, compared to the corresponding normal tissues." (PMID 29212230, 2017). "Of note, positive correlations between Oct4 mRNA and NEAT1/MALAT1 lncRNAs were evident in lung cancer patient specimens." (PMID 28615056, 2017). "Further, the effects of co-processing si-MALAT1 and miR-101 inhibitor on the chemo-resistance of lung cancer cell were evaluated." (PMID 29212230, 2017). "The Catalogue of Somatic Mutations in Cancer (COSMIC) annotates MALAT1 as a cancer consensus gene, associating it with pediatric RCC and lung cancer." (PMID 28358873, 2017). "The promotive function of MALAT1 in lung cancer cell viability and proliferation has been well studied, and verified here using MTT and BrdU assays." (PMID 29212230, 2017). "Deregulation or a functional role for MALAT1 has now been established in several solid tumors, including lung cancer, breast cancer, hepatocellular carcinoma, prostate cancer and gallbladder cancer." (PMID 28938647, 2017). "High MALAT1 expression in lung cancer was related to poorer clinicopathologic features in this study." (PMID 29212230, 2017). "MALAT1 was originally identified in early-stage nonsmall cell lung cancer (NSCLC) with a high propensity for metastasis." (PMID 29632545, 2017). "For example, previous studies demonstrated that MALAT1 was upregulated in lung cancer and breast cancer." (PMID 28938549, 2017). "The results suggested that Oct4/NEAT1 and Oct4/MALAT1 transcriptional axes promote oncogenic effects in lung cancer." (PMID 28615056, 2017). "In summary, we demonstrated that MALAT1 plays an important role in the chemo-resistance of lung cancer by functioning as a ceRNA to regulate the expression of SOX9 by inhibiting miR-101 through the downstream Wnt signaling." (PMID 29212230, 2017). "The overexpression rate for Oct4, NEAT1 and MALAT1 RNA were 85.5%, 90.3% and 88.7%, indicating the oncogenic roles of Oct4, NEAT1 and MALAT1 in lung cancer patients." (PMID 28615056, 2017). "For instance, among the advanced lung cancer patients, cases with rs3200401 CT and CT + TT genotypes in MALAT1 had clearly better prognosis than those with the MALAT1 rs3200401 CC genotype." (PMID 28977863, 2017). "In lung cancer, MALAT1 was initially discovered as a predictive biomarker for metastasis that induces the expression of metastasis-associated genes." (PMID 27686732, 2016).